CXCR4 (C-X-C motif chemokine receptor 4)
Diseases named in the same sentence as CXCR4 in open-access papers (continued):
Sharing a sentence is not in itself a finding about the gene and the disease.
breast carcinoma (continued). "We then showed that an antibody against Nrp2 reduces cytoplasmic CXCR4 expression and inhibited CXCL12-induced chemotaxis in MDA-MB-231 breast cancer cells, which were previously shown to express endogenous Nrp2." (PMID 19580679, 2009). "Nitrite/nitrate levels and CXCR4 expressions were assessed in MDA-MB-231 and SK-BR-3 breast cancer cell lines after induction and/or inhibition of NO synthesis." (PMID 19025611, 2008). "Binding of CXCL12 to CXCR4 has been shown toincrease cellular secretion of VEGF in ovarian cancer, breast cancer,prostate cancer, and malignant glioma." (PMID 18779872, 2008). "Organs that are the first destination of breast cancer metastases have high levels of CXCL12, the CXCR4-specific ligand." (PMID 18941460, 2008). "Recent evidence suggests that metastatic breast cancer cells overexpress CXC chemokine receptor 4 (CXCR4), and that CXCR4 plays a critical role in the homing of cancer cells to specific metastatic sites." (PMID 19025611, 2008). "For breast cancer, it was shown that HER2/neu mediated tumour metastasis, and survival prognosis is essentially driven by upregulation of the chemokine receptor CXCR4, a membrane-bound G-protein-coupled receptor." (PMID 17245339, 2007). "The transcriptional activities of the CXCR4, survivin, Cox-2, SLPI and EGP-2 promoters driving luciferase expression in recombinant Ad vectors was evaluated in four human breast cancer cell lines (MB-468, AU-565, GI-101 and MB-231)." (PMID 16457694, 2005). "The present study demonstrated that breast cancer cells that express SDF-1, and therefore that have an active SDF-1/CXCR4 pathway, are more invasive and motile, thus have a more aggressive phenotype." (PMID 15987445, 2005). "The present study provides strong evidence that, when the SDF-1/CXCR4 complex existed (i.e. in MDA-MB-231SDF1+/+ cells, which expressed both SDF-1 and CXCR4), breast cancer cells exhibited significant increases in invasiveness and faster migration." (PMID 15987445, 2005). "Given that lymph node metastasis directly affects the prognosis of patients with breast cancer, we propose that SDF-1, via the CXCR4 pathway, is potentially a marker of nodal involvement." (PMID 15987445, 2005). "Despite numerous studies on CXCR4 in breast cancer, reports on SDF-1 in human breast cancer are limited." (PMID 15987445, 2005). "The ligands for these receptors – CXCL12 (SDF-1) for CXCR4 and CCL21 for CCR7 – exhibit high expression in organs in which breast cancer metastases are often found." (PMID 15978137, 2005). "In the present study the expression of CXCR4 was detected in various cell lines and in malignant and nonmalignant breast tissues, but SDF-1 expression was only observed in two out of the eight breast cancer cell lines and in the fibroblast cell line MRC5." (PMID 15987445, 2005). "In addition, IL-24 can exert antitumor effects through CXCR4/CXCL12, and CXCL10, CXCL12 and CXCR4 are highly expressed in breast cancer tissues." (PMID 40076586, 2025). "While there have been no reports on the study of FAM241A in GC, CXCR4 is the most widely expressed chemokine receptor in multiple cancers, including GC, breast cancer, and colorectal cancer." (PMID 39886652, 2025). "For example, in breast cancer, TGF‐β activates the TGF‐β/Smad signaling pathway, promoting myofibroblastic CAFs (myCAFs) formation and stimulating CXCL12 secretion, which creates a positive feedback loop through CXCR4 activation." (PMID 41164803, 2025). "Moreover, the CXCR4‒CXCL12 axis, along with phosphorylated mTOR, can induce the EMT program in metastatic breast cancer." (PMID 40740236, 2025). "Furthermore, KLF5 activates CXCR4 transcription, triggering the EMT and driving the liver metastasis of breast cancer." (PMID 40740236, 2025). "Similarly, in breast cancer, iCAFs recruit Tregs and induce an immunosuppressive microenvironment through the CXCL12/CXCR4 axis, ultimately contributing to resistance to anti‐PD‐1 therapy." (PMID 41164803, 2025).
breast carcinoma (continued). "The expression pattern of TGFβ-1, IL19, CXCR4, BMP1, VCAN, and WNT2 in different molecular subclasses of Breast Cancer revealed that TGFβ-1, IL19, CXCR4, BMP1, VCAN, and WNT2 mRNA levels are higher in luminal A followed by luminal B, HER2 and Basal-like respectively." (PMID 41348904, 2025). "PEDF can decrease phosphorylated-nuclear factor-kB p65 subunit (p-NFkB-p65), tumour necrosis factor- (TNF), C-X-C chemokine receptor type-4 (CXCR4), and urokinase plasminogen activator receptor (uPAR) in ER+/HER2- breast cancer cells under post-menopausal oestrogen concentrations." (PMID 40649783, 2025). "Both CXCR4 and JUNB are highly expressed in CTCs isolated from metastatic breast and non-small cell lung cancer (NSCLC) patients, as well as in disseminated tumor cells (DTCs) isolated from early-stage breast cancer migrated in bone marrow." (PMID 38727318, 2024). "CXCR4 is involved in Treg mobilization to the TME in ovarian cancer, breast cancer, and lymphoma." (PMID 39000453, 2024). "In addition, the chemokine receptor CXCR4 was highly expressed in breast cancer tissues, and its ligand CXCL12 was overexpressed in common metastatic sites of breast cancer including bone marrow." (PMID 39605887, 2024). "first explored the expression of CXCR4 in tumors in 2001, CXCR4 was highly expressed in breast cancer, but not expressed or low-expressed in normal breast tissues." (PMID 38524630, 2024). "Furthermore, previous studies by our group have indicated a high expression of CXCR4, JUNB, and PD-L1 in CTCs and/or DTCs of breast cancer and NSCLC patients, related to their survival." (PMID 38727318, 2024). "We further demonstrated high specificity of BS for CXCR4 rather than other chemokine receptors frequently observed in breast cancer." (PMID 38553476, 2024). "CXCL12 was shown to transactivate HER2-neu in the breast cancer cell lines MDA-MB-361 and SKBR3, which express both CXCR4 and HER2-neu that was inhibited by AMD3100, a CXCR4 inhibitor, PKI 166, an epidermal growth factor receptor/HER2- tyrosine kinase inhibitor, and PP2, a Src kinase inhibitor." (PMID 39001456, 2024). "One study reported that DR5 could upregulate CXCR4 and then enhance SDF‐1‐directed migration in breast cancer cells." (PMID 37879960, 2023). "CXCR4-directed therapies have the potential to provide therapeutic options to breast cancer patients without sufficient expression of hormonal receptors or those who become treatment resistant." (PMID 39355052, 2023). "In addition, CXCL12/CXCR4 signaling is found to promote fibrosis in both the primary and metastatic TME of breast cancer." (PMID 37864030, 2023). "Studies blocking the vital chemotactic function of SDF-1 using CXCR4 inhibitor AMD-3100 reported increased effectiveness of a vascular-disrupting agent, combretastatin, in a mouse model of breast cancer, presumably by preventing TIE2-expressing macrophages from being recruited to tumors." (PMID 38067195, 2023). "Previous studies show that metformin downregulates the CXCL12/CXCR4 signaling in breast cancer and prostate cancer cell lines; nevertheless, no data were supporting this pleiotropic effect of metformin in the small intestine so far." (PMID 37795356, 2023). "Besides breast cancer, overexpression of LncRNA UCA1 also accelerated Acute myeloid leukemia (AML) development by regulating METTL14-mediated CXCR4 and CYP1B1 mRNA." (PMID 37365581, 2023). "Mechanistically, LNC942 directly recruits METTL14 protein by harboring the specific recognize sequence (+ 176- + 265), thereby stabilizing the CXCR4 and CYP1B1 mRNA in an m6A modification dependent manner thus finally promoting cell proliferation and colony formation of breast cancer cells." (PMID 37365581, 2023). "Indeed, breast cancer-derived exosomes absorbed by bone marrow cells activate STAT3, leading to CXCR4 reduction." (PMID 38001753, 2023).
breast carcinoma (continued). "Minecoside also inhibits the expression of CXCR4 in breast cancer cells, and its inhibitory effect on CXCR4 expression is not limited to specific cancer cells." (PMID 37570895, 2023). "In conclusion, the present study demonstrated that γ-mangostin exhibits antimigratory action on MDA-MB-231 breast cancer cells, mainly impacting the downregulation of CXCR4, Farp, and LPHN2 genes, but not the case with α-mangostin." (PMID 38655233, 2023). "Importantly, the co-expression levels of CXCR4 and p-STAT3 in breast cancer tissues were correlated with tumor size, lymph node metastasis and histological grade of breast cancer." (PMID 37497001, 2023). "These CXCR4 antagonists block the CXCR4 receptor binding to its ligand SDF-1 and could be potential anticancer agents for the treatment of breast cancer." (PMID 36140541, 2022). "The CXCR4 antagonist GST-NT21MP has been shown to block CXCR4 receptors and inhibit Src activation, thus inhibiting downstream Akt, FAK, and ERK signaling; these events inhibit tumor growth and the metastasis of breast cancer." (PMID 35893797, 2022). "Relative to breast cancer cells expressing GFP control, the expression of CXCR4 and, to a greater extent, ACKR3, significantly reduced bioluminescence due to the association between β-arrestin 2 and PKM2 (p < 0.01 and p < 0.005 for CXCR4 and ACKR3, respectively)." (PMID 35681470, 2022). "Thanks to that CXCR4/CXCL12 chemokine interaction facilitates tumor cell proliferation and leads to the development of distant metastases, it appears that metastasis of breast cancers may mainly arise from the overexpression of chemokine receptors." (PMID 35093187, 2022). "Similarly, upregulation of CXCR4 and downregulation of CXCL12 were observed in primary breast cancers." (PMID 35770088, 2022). "In addition, HER2 elicits the expression of the chemokine receptor C-X-C motif chemokine receptor 4 (CXCR4) in transfection models and also up-regulated CXCR4 expression is typically found in breast cancers with high rates of HER2 expression." (PMID 35093187, 2022). "This means that 68Ga-Pentixafor could help guide therapy by identifying tumours that would respond to therapies targeting the CXCR4/CXCL12 axis; however it cannot replace 18F-FDG PET/CT in the staging of breast cancer." (PMID 36140541, 2022). "Together, these results suggest that SOST in breast cancer cells may promote the proliferation of SCP2 cells by activating the TGF-β/RAS signaling, and promotes bone metastasis by upregulating CXCR4 expression." (PMID 36581888, 2022). "Furthermore, E-selectin plays a critical role in allowing breast cancer cells to infiltrate the bone marrow, and inhibition of the SDF-1/CXCR4 axis induces the mobilization of dormant cancer cells into circulation." (PMID 35464064, 2022). "First, we verified that CXCL12wt, CXCL12-L29C, CXCL12M, and CXCL12D, but not CXCL4-S26C or CXCL12wt mixed with the specific CXCR4 inhibitor AMD3100 led to the increase of cytoplasmic Ca2+ in MDA-MB-231 breast cancer cells." (PMID 36229490, 2022). "The authors found that nonmigrating CSCs contributed to the transformation of non-stem tumour cells to metastatic CXCR4+ cells in primary breast cancer tissue." (PMID 35563449, 2022). "Furthermore, CXCR4 expression has shown a significant prognostic impact in colon cancer, primary cutaneous melanoma, B-ALL and in patients with breast cancer." (PMID 35397601, 2022). "In addition, bone metastasis is more frequently induced by breast cancer cells with hypoxia-inducing factor 1α (HIF-1α), which responds to hypoxia and is stabilized by AKT, resulting in CXCR4 upregulation." (PMID 36012631, 2022). "The interaction between CXCR4 and its specific ligand, i.e., stromal-derived factor-1 (SDF1 or CXCL12), is of considerable importance in the development of invasion and metastasis of different solid tumors, particularly breast cancer." (PMID 35236304, 2022).
breast carcinoma (continued). "We then examined the levels of CXCR4 in ETV4-dificient and -overexpressing breast cancer cells." (PMID 34052833, 2021). "In addition to CXCR4, CXCL12 can also bind to CXCR7, a receptor that is overexpressed within the primary tumors vascular system and holds a more elaborate role in breast cancer progression." (PMID 34066014, 2021). "Mechanistically, on the one hand, we find that ETV4 may enhance glycolysis activity to facilitate breast cancer stemness; on the other, ETV4 activates Sonic Hedgehog signaling by transcriptionally promoting CXCR4 expression." (PMID 34052833, 2021). "Preliminary study in Indonesia about CXCR4 with IHC, the expression is the same for breast cancer with or without distant metastasis, but the high expression of CXCR4 tends to have metastases to the lungs other organs." (PMID 33773539, 2021). "Moreover, we found that knocking down CXCR4 by siRNA inhibited MDA-BoM-1833 migration and ablated the inhibitory effect of ATPγS on breast cancer cell migration." (PMID 34503103, 2021). "Recent mechanistic study has revealed that high POU1F1 expression in breast cancer patients is positively correlated with metastasis in liver and lung, and POU1F1/CXCL12/CXCR4 axis is involved in macrophage recruitment and polarization, as well as metastatic process." (PMID 33927188, 2021). "Notably, among the most upregulated genes we find the well-known stemness marker CXCR4, CYP1A1, which was reported to control bCSCs proliferation, development and self-renewal, and TM4SF1 that was shown to promote breast cancer stem cell traits." (PMID 34680485, 2021). "The expression of CXCR4 in malignant cells is mainly regulated by hypoxia-inducible factors 1 and 2 (HIF1 and HIF2), but it can be induced in breast cancer cells by vascular endothelial growth factor (VEGF), a well-known pro-angiogenic and pro-inflammatory molecule." (PMID 33919589, 2021). "Mechanistically, miR-139 attenuates CXCR4 signaling to inhibit breast cancer invasiveness via inactivation of phosphorylated-Akt (pAktSer473), rather than phosphorylated-ERK signaling, in the miR-139-transduced MDA-MB-231 breast cancer cells." (PMID 34070538, 2021). "Finally, we recommend further studies to determine the integrated effects of CXCL12, CXCR4, and CXCR7 on host immune responses to breast cancer." (PMID 35111484, 2021). "Breast cancer, for example, is characterized by an elevated secretion of proinflammatory cytokines (IL-1, TNF-α, IL-6) or anti-inflammatory cytokines (IL-10), chemokines and chemokine receptors (CXCL8, CXCR4), and angiogenic factors (VEGF)." (PMID 35111484, 2021). "Inhibition of CXCR4 with AMD3100 decreases desmoplasia, reduces immunosuppression, and improves T cell infiltration and response to ICIs in breast cancer while targeting PD-1 and CXCR4 potentiates anti PD-1 efficacy in murine immune sensitive and immune resistant tumors." (PMID 33937018, 2021). "Concordantly, the syndecan‐2‐peptide‐induced reduction in CXCR4 and PD‐L1 expression in TASCs coincided with an increase in the levels of activated T cells within the TME and a decrease in tumour growth in an immune competent syngeneic breast cancer model." (PMID 33152121, 2021). "It was previously shown that treatment of MDA-MB-231 breast cancer cells with DHA reduced surface expression of CXCR4, one of the chemokine receptors crucial for chemoattraction of metastatic cells, but also significantly reduced CXCR4-mediated cell migration." (PMID 34203461, 2021). "CXCR4 and CCR7 surface expression, measured by flow cytometry, was similar between the breast cancer cell lines, indicating that observed differences in ligand cooperativity in metastatic vs non-metastatic cells is not due to the differences in levels of receptor expression." (PMID 34685420, 2021).
breast carcinoma (continued). "Considering the significance previously assigned to the GPCR association for their specific activity, we hypothesised that CXCR4 and CCR7 may heterodimerize to exert their pro-invasive function in mammary tumours." (PMID 34685420, 2021). "SDF-1 was constitutively expressed not only in the bone marrow of breast cancer patients, but also in normal bone marrow, indicating that SDF-1 might induce metastasis of CXCR4-positive breast cancer cells to bone tissues." (PMID 32836215, 2020). "CXCR4 inhibition with AMD3100 decreases desmoplasmia, fibrosis, decompresses blood vessels, increases cytotoxic T cells infiltration and decreases immunosuppression in murine models of breast cancer." (PMID 33096815, 2020). "In addition, nobiletin showed the effect of inhibiting metastasis by downregulating CXC chemokine receptor type 4 (CXCR4) and matrix metallopeptidase-9 on MDA-MB 231 breast cancer cells." (PMID 32212785, 2020). "Moreover, CXCR4, one of the receptor of CXCL12, is a poor prognosis factor in breast cancer patients, independently of ER status, and its high expression has been shown to promote estrogen-independent tumor growth in vivo." (PMID 32727083, 2020). "The in vivo targeting ability of each nanoprobe was established by imaging mice bearing subcutaneous tumors expressing one of three biomarkers of relevance in breast cancer: caveolin 1 (CAV1), C-X-C chemokine receptor type 4 (CXCR4), and Folate Receptor alpha (FRα)." (PMID 33172421, 2020). "Although CXCL12, CCL2, VEGF, MMP2, LOX, and CXCR4 were highly associated with HIF-1α expression, their prognostic significance in breast cancer is less so they were not chosen for further immunohistochemistry analyses." (PMID 33003428, 2020). "In addition, POU domain class 2 transcription factor 1 (known as POU1F1 (Pit-1)) induces the expression of both CXCR4 and CXCL12 in breast cancer cells." (PMID 33096815, 2020). "In addition, similar to the CXCR4/12 interaction, RANKL can also attract circulating breast cancer cells to the bone matrix via the RANKL/RANK system." (PMID 32117996, 2020). "Opposite to CXCR4, the intensity of CXCR7 membrane staining was inversely correlated with Ki67 but positively correlated with tumor size, describing thus a rather slow-growing local tumor pattern, as also reported for CXCR7-positive breast cancer samples." (PMID 33281749, 2020). "Besides MYC itself, we find upregulation of other breast cancer stem cell factors (SOX2, SOX18, THY1, EYA1, GLI2, SALL1, GLIS1, CXCR4), suggesting that MYC HME cells adopt a stem-like state." (PMID 31942031, 2020). "CXCL12/CXCR4 and CXCL16/CXCR6 chemokine signaling also mediates breast cancer progression." (PMID 32879136, 2020). "In contrast, another study showed that, due to low Gαi expression in non-metastatic cells, CXCR4 remains active only in metastatic breast cancer cell lines." (PMID 33096815, 2020). "Furthermore, highly expressed miR-218 is found in metastatic breast cancer cells compared to normal mammary cells, which increases OPN, BSP, and CXCR4 expression to facilitate tumor growth in the bone." (PMID 33123472, 2020). "Based on our murine model, we hypothesized that CXCR4 and CCR9 receptors might be upregulated in breast cancer cells derived from primary tumors of obese individuals." (PMID 31616626, 2019). "The involvement of AQP3 was also demonstrated in human breast cancer cell lines expressing CXCR4 but not EGFR." (PMID 30893772, 2019). "CXCL12/CXCR4 axis in these cells mediates restrained cytotoxic T cell infiltration and builds up immunosuppressive tumor microenvironment in CT26, SL4 colorectal carcinoma, and E0771, MCa-M3C mammary carcinoma." (PMID 31474975, 2019).